VCP (valosin containing protein)
Diseases named in the same sentence as VCP in open-access papers (continued):
Sharing a sentence is not in itself a finding about the gene and the disease.
frontotemporal dementia (continued). "A recent study further demonstrates that wild-type VCP/p97 is capable of disassembling tau aggregates derived from Alzheimer’s disease donors, but a frontotemporal dementia-linked pathological D395G mutation in VCP showed markedly reduced disaggregation activity." (PMID 35517053, 2022). "In fibroblasts derived from patients with diseases such as inclusion body myopathy, Paget disease of bone, and frontotemporal dementia, mutation of p97/VCP revealed the impairment of autophagosome maturation like HDAC6, as well as ER-associated degradation (ERAD)." (PMID 33670947, 2021). "For example, several genes causing ALS and/or frontotemporal dementia (C9orf72, VCP, SQSTM1, OPTN, UBQLN2, GRN, CHMP2B) affect the autophagic machinery; and some Alzheimer’s Disease genes (APOE, TREM2, CD33, ABCA7) are preferentially or exclusively expressed in microglia." (PMID 33892821, 2021). "Furthermore, mutations in VCP cause early‐onset Paget disease in conjunction with frontotemporal dementia and inclusion body myositis." (PMID 34459017, 2021). "We have previously developed a fly model for IBMPFD (inclusion body myopathy with Paget disease and frontotemporal dementia) and demonstrated that specific mutations in VCP gene, a highly conserved ATPase, cause muscle and neuron degeneration by depleting cellular ATP level." (PMID 25255315, 2014). "Single missense mutations in the VCP gene are the cause of frontotemporal dementia (IBMPFD) and may account for 1%–2% of familial amyotrophic lateral sclerosis (ALS)." (PMID 23498975, 2013). "Dominantly inherited mutation D395G in the gene encoding valosin-containing protein (VCP) has been described as the cause of an inherited form of behavioural-variant frontotemporal dementia (FTD) in three families from Greece, the US and Japan." (PMID 38758288, 2024). "Variants in the valosin-containing protein (VCP) gene were identified as one of the causes for inclusion body myopathy associated with Paget disease of the bone and frontotemporal dementia (FTD)." (PMID 36329418, 2022). "Inclusion body myopathy (IBM) with Paget’s disease of bone (PDB) and/or frontotemporal dementia (FTD) (IBMPFD) was described as rare autosomal dominant disorder due to mutations in the VCP gene." (PMID 34917136, 2021). "Valosin-containing protein (VCP) variants can cause adult-onset proximal myopathy, which leads to upper and lower extremity weakness, axial myopathy, scapular winging, PDB and frontotemporal dementia (IBMPFD)." (PMID 40229738, 2025). "Multisystem Proteinopathy 1 (MSP1) disease is a rare genetic disorder caused by mutations in the Valosin-Containing Protein (VCP) gene with clinical features of inclusion body myopathy (IBM), frontotemporal dementia (FTD), and Paget’s disease of bone (PDB)." (PMID 38467645, 2024). "A noteworthy revelation establishes a connection between mutations in the valosin-containing protein (VCP) gene and ALS, extending its previously known associations with other NDs like body myopathy, Paget’s disease, and frontotemporal dementia." (PMID 39523358, 2024). "In patients affected by frontotemporal dementia and/or amyotrophic lateral sclerosis-6 (FTDALS6), caused by mutations in the Valosin-containing protein (VCP), there is also TAU pathology and deposition of pathologic TDP-43." (PMID 38554150, 2024). "VCP mutations can cause the rare disorder inclusion body myopathy (IBM) associated with Paget’s disease of the bone (PBD) and frontotemporal dementia (IBMPFD)." (PMID 37545006, 2023). "Several neurologic diseases such as frontotemporal dementia (IBMPFD) and inclusion body myopathy (IBM) with Paget disease of bone are caused by VCP mutations." (PMID 36596053, 2022). "Point mutations in VCP induce multisystem proteinopathy type 1 (MSP1), which is known as inclusion body myopathy associated with Paget’s disease and frontotemporal dementia (IBMPFD)/amyotrophic lateral sclerosis (ALS)." (PMID 35089078, 2022).
frontotemporal dementia (continued). "Pathogenic gain of function variants in Valosin-containing protein (VCP) cause a unique disease characterized by inclusion body myopathy with early-onset Paget disease of bone and frontotemporal dementia (also known as Multisystem proteinopathy (MSP))." (PMID 34998409, 2022). "Mutations in the valosin-containing protein (VCP) gene were identified as the cause of the syndrome of hereditary inclusion body myopathy, PDB, and frontotemporal dementia (IBMPFD)." (PMID 33988819, 2021). "Type D is associated with frontotemporal dementia (FTD) and Paget’s disease of bone caused by mutations of VCP gene." (PMID 34930382, 2021). "Missense mutations of VCP account for 1–2% of familial ALS, but can additionally cause an autosomal dominant disease known as inclusion body myopathy, Paget disease and frontotemporal dementia (IBMPFD)." (PMID 34396115, 2021). "Dominant mutations in valosin-containing protein (VCP) gene cause an adult onset inclusion body myopathy, Paget’s disease of bone, and frontotemporal dementia also termed multisystem proteinopathy (MSP)." (PMID 32993728, 2020). "One VCP/p97 mutation causes a rare multisystem disease, IBMPFD (inclusion body myopathy with Paget’s disease and frontotemporal dementia)." (PMID 32824240, 2020). "Given that mutations in PINK1 and VCP are known to cause Parkinson’s disease (PD) and frontotemporal dementia (FTD), conditions affecting primarily neurons, the discovery that they act in a common pathway to support dendritic arborization has important implications for neuronal health and disease." (PMID 30783609, 2018). "Mutations in the valosin-containing protein (VCP) gene are associated with a heterogeneous group of disorders including HIBM, Paget’s disease of bone, frontotemporal dementia (IBMPFD) and ALS." (PMID 29163032, 2017). "VCP/p97 mutations cause a rare multisystem disease called IBMPFD (Inclusion Body Myopathy with Paget’s Disease and Frontotemporal Dementia)." (PMID 27768726, 2016). "Mutations in the valosin-containing protein (VCP) gene were first found to cause inclusion- body myopathy with early-onset Paget disease and frontotemporal dementia (IBMPFD)." (PMID 25492614, 2014). "Valosin containing protein (VCP) mutations are the cause of hereditary inclusion body myopathy, Paget's disease of bone, frontotemporal dementia (IBMPFD)." (PMID 23029473, 2012). "In conjunction with another gene product (valosin-containing protein) associated with a form of FTD (inclusion body myopathy with Paget disease of bone and frontotemporal dementia) and ALS, HDAC6 decides over proteasomal versus autophagic breakdown fates." (PMID 21878116, 2011). "In addition, mutation of human VCP associated with degenerative disorders such as IBMPFD (Inclusion body myopathy with early onset Paget disease and frontotemporal dementia), familial ALS (amyotrophic lateral sclerosis), and Charcot-Marie-Tooth disease." (PMID 40975168, 2025). "The VCP gene is typically associated with autosomal dominant Charcot-Marie Tooth type 2Y (OMIM #616687), frontotemporal dementia and/or amyotrophic lateral sclerosis 6 (OMIM #613954), or inclusion body myopathy with early-onset Paget disease and frontotemporal dementia (OMIM #167320)." (PMID 39420034, 2024). "Using a Drosophila eye model expressing mutant Drosophila VCP (dVCP) that causes amyotrophic lateral sclerosis (ALS) and frontotemporal dementia (FTD), or multisystem proteinopathy (MSP), we demonstrated that abnormal eye phenotypes generated by dVCPR152H were rescued by Eip74EF siRNA expression." (PMID 36879317, 2023). "Previously identified pathogenic variants in VCP are associated with frontotemporal lobar degeneration with TDP-43 inclusions (FTLD-TDP) pathologically, but p.Asp395Gly VCP was recently reported to cause familial FTD with tauopathy characterized by neurofibrillary tau tangles (NFT) and not FTLD-TDP." (PMID 36329418, 2022).
frontotemporal dementia (continued). "VCP-associated inclusion body myopathy with Paget disease of bone and frontotemporal dementia, also termed VCP disease and multisystem proteinopathy (MSP 1), is an autosomal dominant disorder caused by monoallelic variants in the VCP gene on human chromosome 9." (PMID 35841038, 2022). "Intriguingly, a significant number of genes involved in the pathogenesis of PDB (namely SQSTM1, VCP, PFN1, and OPTN) have been also associated with neurodegenerative disorders (e.g., ALS or frontotemporal dementia) suggesting shared pathophysiological mechanisms." (PMID 36035996, 2022). "VCP is encoded by the causative gene of IBMPFD (inclusion body myopathy with Paget’s disease of bone and frontotemporal dementia), a dominant inherited disorder with three major symptoms: myopathy, osteolytic bone lesions, and frontotemporal dementia." (PMID 33121128, 2020). "The mutations of VCP have been associated with diverse myodegenerative and neurodegenerative disorders including inclusion body myopathy (IBM), with Paget disease of the bone, as well as frontotemporal dementia (IBMPFD) and amyotrophic lateral sclerosis (ALS)." (PMID 32481679, 2020). "A rare subtype is HIBM with Paget's disease of the bone and frontotemporal dementia (HIBM-PFD), which is due to the valosin-containing protein (VCP) gene mutations, resulting in abnormal accumulation of ubiquitinated proteins and impaired autophagy in IBM-PFD muscle." (PMID 29872374, 2018). "Indeed, specific mutations in VCP have been linked to IBMPFD (Inclusion body myopathy with Paget disease and frontotemporal dementia), an autosomal dominant, multi-system degenerative disorder." (PMID 25255315, 2014). "Mutations in VCP (Valosin-containing protein), an AAA ATPase critical for ER-associated degradation, are linked to IBMPFD (Inclusion body myopathy with Paget disease and frontotemporal dementia)." (PMID 25255315, 2014). "Various family studies have shown a significant pathophysiological and clinical overlap between ALS and frontotemporal dementia (FTD), especially in cases related to variants in the C9ORF72, TARDBP, FUS, and VCP genes." (PMID 39596609, 2024). "In contrast to the lentiform TDP-43 NIIs, which are observed in certain frontotemporal dementias and which are conditional upon GRN or VCP mutations, our data support the hypothesis that the presence of α-Syn NIIs in MSA is instead purely amyloid-strain-dependent." (PMID 35327628, 2022). "Mutations in the VCP (Valosin Containing Protein) gene cause the autosomal dominant syndrome “Inclusion Body Myopathy, PDB, Fronto-temporal Dementia,” characterized by pagetic manifestations, associated with myopathy, amyotrophic lateral sclerosis and fronto-temporal dementia." (PMID 36035996, 2022). "Clinical and genetic overlap exists with frontotemporal dementia (FTD), which is caused by mutations in C9orf72, MAPT, GRN, TARDPB, VCP, as well as other genes." (PMID 35493319, 2022). "IBMPFD is a multisystem degenerative disorder caused by mutations in VCP, which includes IBM associated with Paget’s disease of the bone (PDB) and frontotemporal dementia (FTD)." (PMID 32481679, 2020). "Mutations in VCP (encoding valosin-containing protein, also known as p97 or Cdc48), cause ALS, FTD and a related syndrome known as inclusion body myopathy with Paget disease of bone and frontotemporal dementia (IBMPFD)." (PMID 29584802, 2018). "Pathogenic variants in valosin-containing protein (VCP) cause multisystem proteinopathy (MSP), a disease characterized by multiple clinical phenotypes including inclusion body myopathy, Paget’s disease of the bone, and frontotemporal dementia (FTD)." (PMID 38787785, 2024). "In the course of discussing a VCP-MSP diagnosis, it is also necessary to mention the chance of eventually developing a more severe disorder such as frontotemporal dementia or ALS." (PMID 35741724, 2022).
frontotemporal dementia (continued). "Currently, more than 45 VCP mutations have been identified as responsible of a rare multisystem proteinopathy known as inclusion body myopathy (IBM) associated with Paget’s disease of bone (PDB) and early onset frontotemporal dementia (FTD) (IBMPFD)." (PMID 34917136, 2021). "Furthermore, VCP mutations are associated with mitochondrial depolarization, oxidative stress in ALS and frontotemporal dementia (FTD)." (PMID 34867159, 2021). "Thus, MATR3 is among the family of genes including VCP, HNRNPA1, HNRNPA2B1 and SQSTM1 that cause “multisystem proteinopathy” associated with either one or a combination of ALS/frontotemporal dementia (FTD), VCPDM and Paget’s disease of bone." (PMID 32811564, 2020). "Clinically, phenotypes of the VCP-related MSP are heterogeneous even within families, including inclusion body myopathy, Paget’s disease of bone, and frontotemporal dementia." (PMID 32993728, 2020). "Compared to the GRN- and VCP-unique datasets, the FLNC-unique protein dataset showed the strongest correlation to frontotemporal dementia, neurodegeneration and aging." (PMID 26555887, 2015). "The group of Dr. Kimonis described in 2001 that mutations in the VCP gene were the cause of an autosomal dominant disease characterized by the combination of an inclusion body myopathy (IBM), Paget's disease of the bone (PDB) and frontotemporal dementia (FTD), also known as IBMPFD." (PMID 37603075, 2023). "VCP mutations cause inclusion body myopathy with early-onset Paget disease and frontotemporal dementia (IBMPFD), also known as multisystem proteinopathies (MSPs), familial forms of amyotrophic lateral sclerosis (fALS) and/or frontotemporal dementia (FTD) and Parkinson’s disease (PD)." (PMID 35501124, 2022). "Mutations in VCP are associated with two neurodegenerative diseases, amyotrophic lateral sclerosis (ALS) and inclusion body myopathy with Paget's disease of the bone and frontotemporal dementia (IBMPFD), and extensive study has revealed crucial functions of VCP within neurons." (PMID 29037990, 2017). "Up to 15% of ALS patients also develop signs of frontotemporal dementia (FTD) and several genes, including C9ORF72, TDP-43, VCP, SQSTM1, OPTN, UBQLN2 and TBK1, contribute to the etiology of both ALS and FTD." (PMID 37220877, 2023). "Heterozygous mutations in the human VCP (p97) gene cause autosomal-dominant IBMPFD (inclusion body myopathy with early onset Paget’s disease of bone and frontotemporal dementia), ALS14 (amyotrophic lateral sclerosis with or without frontotemporal dementia) and HSP (hereditary spastic paraplegia)." (PMID 23056506, 2012). "Also, in amyotrophic lateral sclerosis (ALS) and frontotemporal lobar degeneration (FTLD), the toxic aggregation of one protein – TDP-43 – can result from defects in other proteins, some of which are related to proteostasis, such as the shuttle protein Optineurin and the E3 ubiquitin ligase VCP." (PMID 40969213, 2025). "Similar findings may be observed in biopsies from patients with valosin-containing protein (VCP)-related inclusion body myopathy associated with Paget's disease of bone and frontotemporal dementia which, therefore, should not be excluded as a differential diagnosis." (PMID 21798100, 2011). "Given the patient’s family history of frontotemporal dementia (FTD) in a maternal uncle, the genetic analysis was extended to include the most common genes associated with FTD (TARDBP, GRN, TBK1, CHMP2B, SQSTM1, UBQLN2, VCP and MAPT) but no additional variants of clinical significance were detected." (PMID 40659544, 2025).
amyotrophic lateral sclerosis (85 papers, 2012 to 2025). Amyotrophic lateral sclerosis (ALS) is a neurodegenerative disease characterized by progressive muscular paralysis reflecting degeneration of motor neurons in the primary motor cortex, corticospinal tracts, brainstem and spinal cord. "In the ORPHA:100991 (SPG10) phenotypic cluster, a pathogenic variant in VCP, known to be associated with amyotrophic lateral sclerosis was found for an unsolved case, which appeared consistent with the case’s clinical presentation." (PMID 37926714, 2024). "Genetic mutations in VCP are associated with several forms of muscular and neuronal degeneration, including amyotrophic lateral sclerosis (ALS)." (PMID 36789492, 2023). "Approximately 9% of patients with VCP variants had a classic amyotrophic lateral sclerosis (ALS) phenotype." (PMID 35841038, 2022). "VCP mutations have also been reported in patients with amyotrophic lateral sclerosis (ALS), Charcot–Marie–Tooth type 2 (CMT2) disease, and hereditary spastic paraplegia (HSP)." (PMID 36140389, 2022). "VCP mutations have been associated with several diseases such as myopathy, Paget’s disease, dementia, amyotrophic lateral sclerosis and Huntington’s disease." (PMID 35273242, 2022). "VCP mutations are also associated with 1–2% of cases of amyotrophic lateral sclerosis (ALS), familial hereditary spastic paraplegia (HSP) and Charcot-Marie-Tooth 2 (CMT2) disease." (PMID 28322724, 2017). "VCP has also been linked to Huntington's disease, Parkinson's disease, amyotrophic lateral sclerosis, and Alzheimer's disease." (PMID 24717448, 2014). "VCP is implicated in apoptosis‐related pathways through endoplasmic reticulum stress during protein processing and is associated with various neuronal diseases, including Parkinson's disease, Alzheimer's disease, and amyotrophic lateral sclerosis." (PMID 41178061, 2025). "Indeed, VCP mutations have also been reported in patients with amyotrophic lateral sclerosis (ALS), Charcot-Marie-Tooth type 2 (CMT2) disease, and hereditary spastic paraplegia (HSP)." (PMID 34917136, 2021). "While seemingly unrelated to PSP, a curious number of neurodegeneration-related genes are also involved in bone diseases (e.g. TREM2, which has been linked to AD and Nasu-Hakola disease, and VCP, linked to amyotrophic lateral sclerosis and Paget’s disease of bone)." (PMID 30089514, 2018). "Moreover, p97/VCP mutations were detected in a fraction of patients suffering from familial forms of Parkinson’s Disease or from Amyotrophic Lateral Sclerosis (ALS)." (PMID 30333975, 2018). "In addition to IBMPFD, recent human genetic analysis indicated that VCP mutations account for 1-2% of autosomal dominantly inherited amyotrophic lateral sclerosis (ALS)." (PMID 22449146, 2012). "VCP mutations can instigate other neurodegenerative conditions, such as amyotrophic lateral sclerosis (ALS), Parkinson’s disease (PD), Charcot-Marie-Tooth disease type 2y (CMT2Y), and hereditary spastic paraplegia (HSP)." (PMID 37545006, 2023). "Mutations in the valosin-containing protein (VCP) gene have been linked to amyotrophic lateral sclerosis (ALS) in the Caucasian populations." (PMID 35197922, 2022). "VCP variants are also associated with amyotrophic lateral sclerosis (ALS), Parkinson's disease, Huntington disease and Charcot-Marie-Tooth disease type 2." (PMID 35841038, 2022). "Interestingly, the gene encoding for the protein valosin-containing protein (VCP), an interactor of strumpellin, can cause several neurodegenerative diseases such as amyotrophic lateral sclerosis (ALS), Charcot–Marie–Tooth (CMT) disease and notably HSP, when mutated." (PMID 34359848, 2021). "More recently, mutations in VCP have been implicated as having a role in familial amyotrophic lateral sclerosis (ALS)." (PMID 25878907, 2015).